MMP2 (matrix metallopeptidase 2)
Diseases named in the same sentence as MMP2 in open-access papers (continued):
Sharing a sentence is not in itself a finding about the gene and the disease.
tumor (continued). "MMP-2 and MMP-9 have been strongly linked to angiogenesis, invasion, and metastasis in tumor cells." (PMID 33994999, 2021). "Overexpression of Mmp2 in B16 cells accelerates tumor growth and promotes a protumorigenic TME." (PMID 34032639, 2021). "Taken together, the results reveal that the TME of Mmp2 overexpressing tumors in WT mice is enriched in M2-like macrophages but reduced in tumor-reactive cytotoxic CD8+ T cells and polyfunctional mature NK infiltration, which together would compose a protumorigenic TME." (PMID 34032639, 2021). "Stromal MMP2/9 may also participate in tumor tissue remodeling and contribute to cancer progression." (PMID 33568081, 2021). "In tumor cells, αvβ3 plays a role in destroying the basement membrane and interstitial matrix through activation of MMP-2 and plasmin, which may accelerate tumor invasion and metastasis." (PMID 33530291, 2021). "Lastly, TIMP2, MMP2 and MMP14 are mediators of ECM degradation associated with tumor metastasis." (PMID 34140574, 2021). "Similarly, utilizing cancer-associated MMP-2 activity, a PEG 2000-paclitaxel conjugate showed improved tumor targeting characteristics over standard paclitaxel." (PMID 33802262, 2021). "We confirmed a protumorigenic role for MMP2 as its overexpression exacerbated tumor growth." (PMID 34032639, 2021). "Importantly, this invasion-promoting cross communication appears to be mediated by the synergistic interaction of membrane-bound MT1-MMP residing on tumor cells with the soluble MMP2 secreted by PSCs and normal fibroblasts." (PMID 33740019, 2021). "MMP-2 improves the infiltration abilities of both tumor cells and macrophages." (PMID 33669419, 2021). "Moreover, LMWF enhanced the suppressive effects of 5-FU on tumor cell migration through the c-MET/matrix metalloproteinase (MMP)-2 signaling pathway in both HCT116 and Caco-2 cells." (PMID 34360807, 2021). "MMP‐2, which was related to the invasion ability of tumor cells, was downregulated." (PMID 33943009, 2021). "Furthermore, it was validated using mouse model experiment that circSETDB1 depletion repressed tumor growth and decreased the expression of metastasis-related MMP9 and MMP2 as well as proliferation-linked ki-67." (PMID 34789310, 2021). "Also, the positive correlation between Chitinase 3-like 1 and IL8 (0.57) or MMP2 (0.50) suggest a role in tumor growth and metastasis pathways." (PMID 33846436, 2021). "In vitro invasion assay confirmed that irradiation targeting D2A1 tumor and its microenvironment increased the levels of plasma IL-1β, promoted the infiltration of tumor cells and the development of lung metastasis and increased the activity of MMP-2 and MMP9." (PMID 34602858, 2021). "Additionally, the representative proteins, in the tumor EMT process including MMP-2 and vimentin, were evaluated via western blotting." (PMID 34162396, 2021). "Among the MMPs, MMP-2 acts as a key enzyme that could be related to tumor metastasis and physiologic functions." (PMID 34027107, 2021). "CAFs may also be involved in tumor escapes from the immune response by releasing MMP-2, MMP-9 and MMP-14." (PMID 34204372, 2021). "MMP-9 and MMP-2 are essential to cleavage of collagen type IV, the major component of the basement membrane, and in the context of cancer biology, they are activated at the onset of angiogenesis, resulting in invasive tumor growth." (PMID 33716674, 2021). "Mmp2 overexpression in tumor cells is therefore likely to impact other pathways beyond Tlr2/4 signaling that contribute to tumor growth — e.g., degradation of ECM proteins to modify the TME architecture or degradation of IFNAR1 in immune cells (APCs or other cell types) as we previously showed." (PMID 34032639, 2021). "Furthermore, knockdown of FOXH1 decreased the expression and secretion of MMP2, a key MMP associated with tumor dissemination and invasiveness." (PMID 34090445, 2021).
tumor (continued). "During invasion and metastasis, tumor cells not only secrete ECM degradative enzymes such as MMP-2, but also produce and secrete growth factors, cytokines, and hormones to entice host or neighboring cells into producing proteolytic enzymes to degrade the ECM12–14." (PMID 34429501, 2021). "Thus, PDAC cell CM with the greatest MMP2, including PANC-1 and L3.6, conferred more robust matrix remodeling than tumor cells with low MMP2, including HPAF-II and CFPAC." (PMID 33740019, 2021). "Even though MMP-2 and MMP-9 represent the most investigated MMPs in the context of radiotherapy, also other family members have been associated with the remodeling of the irradiated tumor microenvironment." (PMID 34055644, 2021). "Furthermore, the expression of Tlr2 and Tlr4 in both hematopoietic and stromal compartments appears to support Mmp2-driven tumor growth." (PMID 34032639, 2021). "The same inhibitory potential of CTX on MMP-2 secretion was observed against tumor stimulation." (PMID 34421610, 2021). "Interestingly, MMP-14 and α5β1-integrin have the common functions of activating MMP-2 and stimulating tumor angiogenesis." (PMID 34502094, 2021). "MMP-2 and -9 play crucial roles in ECM remodeling and cleavage of membrane substrates and have therefore been associated with several hallmarks of cancer such as angiogenesis, tumor invasion, and metastasis." (PMID 34055644, 2021). "Here, we hypothesized that the activated STAT3 was translocated to the nucleus and bound to the MMP2 promoter to stimulate tumor cell invasion, and was bound to the PD-L1 promoter to boost tumor metastasis or regulate immune escape." (PMID 33805840, 2021). "Similarly, mRNA levels of vimentin, N‐cadherin, E‐cadherin, CK‐19, MMP‐9, and MMP‐2 in tumour tissues were consistent with the gene expression results in Linc00485‐silenced A549 cells." (PMID 33237626, 2021). "Higher expression of MMP2/9 was found in tumor tissues compared with adjacent normal tissues." (PMID 33568081, 2021). "Similarly, DH82-medium xenografts comprised a smaller-sized MMP-2-positive area at 54 dpt (p = 0.0036) and 63 dpt (p < 0.0001) within the tumor periphery compared to 44 dpt." (PMID 33808256, 2021). "Interestingly, the stromal cell lines, particularly RF, HF, hPSC, and ITAF cells, displayed relatively high levels of MMP2, especially pro-MMP2, in comparison to the tumor cells." (PMID 33740019, 2021). "Overexpression of MMPs in tumor cells will enhance degradation of the basement membrane to facilitate invasion of nearby blood vessels, followed by extravasion to distant tissues to seed new metastatic sites and tumor cells mainly express MMP-9 instead of MMP-2 in HCC47." (PMID 34819565, 2021). "In addition, the tumor also showed decreased matrix metalloproteinase 2 (MMP2) and matrix metalloproteinase 9 (MMP9) expression levels while there were increased E-cadherin levels." (PMID 32372949, 2020). "However, this requirement can be circumvented by the presence of CAFs in the tumor environment or by the presence of a divergent group of cancer cells that over-express MMP-2." (PMID 33321813, 2020). "Importantly, the NF-κB pathway regulates the expression of many tumor angiogenesis-associated genes, such as VEGF, PDGF-BB, MMP-2, and MMP-963,64." (PMID 31974361, 2020). "In addition, it plays an important role in tumor cell migration through upregulating MMP2 and MMP9 expression or activating integrin 42-44." (PMID 33173412, 2020). "Additionally, exosomes obtained from MSCs contain MMP-2 molecules that contribute to the remodeling of the tumor microenvironment and cell growth." (PMID 32426106, 2020). "The matrix metalloprotease 2 (MMP2) is overexpressed in the tumor microenvironment." (PMID 32508641, 2020). "MMP-2 null mice have been reported to be anatomically smaller than wild-type mice with less total vascular development, abnormal lung alveolarization and interestingly, decreased rates of tumor angiogenesis." (PMID 32111836, 2020).
tumor (continued). "Responsible factors include metalloproteinases such as MMP2; these have been shown to promote cancer progression due to their degrading basement membrane components and collagen break down into peptides that act as chemoattractants for circulating tumor cells." (PMID 32258243, 2020). "From this, we can extrapolate that VEGF in the central cells of islands formed by tumour parenchyma may signal peripheral cells for greater proliferation and invasion, which is likely to be mediated by MMP-2 expression." (PMID 33067558, 2020). "Moreover, baicalein also has been proved to induce apoptosis by activating caspase-9/-3 and to inhibit tumor invasion and metastasis by reducing the expression of matrix metalloproteinase-2/-9 (MMP-2/-9)." (PMID 33276419, 2020). "In addition, we also found that enalapril and 5-FU together significantly inhibited the expression of MMP-2 and MMP-9 in vivo, which are also associated with tumor invasion and metastasis, and are regulated by NF-κB/STAT3 pathway." (PMID 32581212, 2020). "In particular,MMP-2 may affect tumor growth, invasion and metastasis by regulating lymphaticvessel formation as well as angiogenesis." (PMID 33152052, 2020). "Furthermore, by screening potential downstream effectors, we found that Porf-2 is able to suppress tumor cell migration by the inactivation of Rac1 and by reducing the expression of MMP-2/9." (PMID 32676454, 2020). "In conclusion, KDELC2 could induce GBM migration and invasion by stimulating MMP-2, and increased tumor proliferation through inhibiting Caspase 3 and 9 and accelerating cell cycle speed." (PMID 32927743, 2020). "In other tissues, CAT has previously been capable to activate pro–MMP-2 in human tumor cell invasion and together with MMP-9 may enhance TGFβ signaling in a tumor murine model." (PMID 33195599, 2020). "In particular, TIMP2 and MMP2 also function in tumor invasion." (PMID 33203436, 2020). "The potential clinical relevance is less pronounced, as just half of the studies reported associations between increased MMP2 or MMP9 levels with clinical characteristics such as survival, metastasis or tumor stage, whereas in the other half of the studies no such correlations were observed." (PMID 32325664, 2020). "Furthermore, anti-MMP-2 antibodies decreased the size of OPN-induced tumors indicating MMP-2’s role in tumor formation." (PMID 33203146, 2020). "To that end, we first explore mathematically the positive feedback that the macroscopic distribution of ECM fibres close to the tumour interface has upon the emerging cell-scale source of MMP-2 for the cross-interface micro-dynamics that MMP-2 exercises at the invading edge of the tumour." (PMID 32458057, 2020). "In this study, anti-tumor drugs camptothecin and trans-retinoic acid were cooperatively entrapped in enzyme-responsive NPs, which exhibited a desired MMP-2-triggered degradation process and achieved reduced side effects, enhanced intertumoral accumulation, and improved anti-tumor efficacy." (PMID 32850662, 2020). "Inhibition of STAT3 inhibits its target gene MMP2 and inhibits tumor cell invasion." (PMID 33330321, 2020). "In addition, analysis of matrix metalloproteinase-2 (MMP-2, an enzyme involved in tumour invasion) mRNA expression showed significantly decreased MMP-2 mRNA transcription upon CD73 inhibition (p < 0.001)." (PMID 33187081, 2020). "Moreover, the protection of MMP‐2 from the degradation in tumor cells by interacting with Hsp90α has been demonstrated." (PMID 32180962, 2020). "However, perturbed MMP-2 gene expression was the only molecular biomarker independently associated with poor outcome independently on the EMT transcriptional biomarkers, tumor size or disease stage." (PMID 33321813, 2020). "Additionally, in vivo experiments demonstrated that tumor growth was significantly inhibited by the knockdown of circ_MMP2." (PMID 31944556, 2020). "Then, we determined the expression of MMP2 which is required for tumour metastasis." (PMID 32851798, 2020).
tumor (continued). "A human pancreatic epithelioid carcinoma cell line, Panc I, with lower MMP-2 and MMP-9 expression levels than HT1080 cells was unable to activate the recombinant SeV, demonstrating this system as an efficient tool for delivery to tumor sites where MMP-2 and MMP-9 are overexpressed." (PMID 32466129, 2020). "Thus, performed network pharmacology analysis revealed that SM can control EMT of tumor cells hypothetically by its direct interactions with MMP-2/-9 and JNK1, playing an important role in EMT program." (PMID 33327637, 2020). "Moreover, we show that IKKβ targeting reduces tumour cell migration and invasion, potentially by regulating both expression and activity of matrix metalloproteinase 2 (MMP2)." (PMID 32823550, 2020). "It is reported that MMP2 knockout can inhibit tumor metastasis." (PMID 31900207, 2020). "To clarify the mechanism underlying EVI5-mediated tumor metastasis, we analyzed the molecular expression of TGF-β receptor II, TGF-β receptor I, p-Smad3, Snail, Vimentin, MMP2 and N-Cadherin levels were significantly decreased and E-Cadherin was significantly increased in EVI5-knockdown cells." (PMID 32393392, 2020). "In addition, we noticed that with the increase of tumor volume, the expression of MMP2 showed an increasing trend." (PMID 33115469, 2020). "Pending prospective validation studies, we suggest that molecular targeted therapy using FAK inhibitors in combination with MMP-2 inhibitors may help control tumor progression and prolong progression-free survival." (PMID 33321813, 2020). "In addition, ablation of endogenous EIF5A2 inhibited tumor angiogenesis by reducing MMP-2 expression." (PMID 32522053, 2020). "Briefly, considering that the peptide with the PLGLAG is sensitive to MMP-2, abundantly present in tumor tissue, CXB was conjugated to the GGPLGLAGG peptide, and the triblock copolymer [PPLG-g-(CXB-peptide & mPEG)]-PEG-PCL (PCxbP) was manufactured through a click reaction with a prepolymer." (PMID 33261219, 2020). "Taken together, we show in this study that the effect of ECM components on various RCC cell lines is heterogenous varying according to RCC cell type and matrix with Col 1 being the main enhancer of tumor cell invasion, of MMP-2 and 9 activity and consequently to metastasis." (PMID 32411604, 2020). "Indeed, low oxygenation indirectly promotes MMP-9 and MMP-2 upregulation and increased proteolytic activity, by reducing pH levels in the tumor microenvironment." (PMID 33020459, 2020). "Our data suggest that RET could be up-regulated in tumour macrophages, thereby limiting inflammation and enhancing MMP2 production within the tumour microenvironment." (PMID 33020210, 2020). "MMP2, a metastasis‐related protein, promotes tumor metastasis." (PMID 31944556, 2020). "Secondly, the amount of leptin in the gastrocnemius correlated positively with the amount of soluble PECAM and MMP2 in the same tissue as well as with different actors of the tumour oxidative status (total glutathione, glutathione-S-transferase, glutathione reductase, thioredoxin and COX-2)." (PMID 32472095, 2020). "The proteinases MMP2 and MMP9 are associated with cancer progression with known roles in degradation and remodelling of the surrounding extracellular matrix (ECM) to facilitate tumour angiogenesis, invasion and metastasis." (PMID 32246008, 2020). "In addition, BACE2 also downregulated MMP2, which plays a significant role in type IV collagen degradation during tumour invasion and migration." (PMID 31856384, 2020). "Thus, when the liposomal drugs were administered concurrently, the activity of MMP-2 was reduced by 35%–40% (p < 0.01) compared to control tumor activities of this enzyme." (PMID 32340166, 2020). "The expression of MMP‐2 in our primary tumor cells could be related to the highly vascular nature of the UPS demonstrated by CD34 staining of primary tumor." (PMID 32652895, 2020).
tumor (continued). "Finally, the proliferation marker PCNA and the invasion marker MMP2 were detected by IHC staining in tumor xenografts." (PMID 33093458, 2020). "SASH1 gene may inhibit the invasion and metastasis of tumor cells by inhibiting the expression of MMP-2/9 in A549 cells." (PMID 33134379, 2020). "Furthermore, the levels of the tumor invasion-related proteins MMP-2 and MMP-9 decreased significantly after treatment with hesperetin and DDP, which was reversed by downregulation of PTEN (#P < 0.05)." (PMID 32973533, 2020). "Thus, the combined therapy induced a strong inhibition of tumor growth mainly via the anti-angiogenic actions as well as inhibitory effects on two important proteins involved in tumor progression and metastasis (MMP-2 and AP-1)." (PMID 32340166, 2020). "MMP-9, MMP-2, uPA, and VEGF, as metastasis and angiogenesis-associated proteins, promote extracellular matrix degradation and new blood vessel development, leading to enhanced tumor invasion and growth." (PMID 32429376, 2020). "Intraperitoneally administered β-elemene was reported to inhibit in vivo growth and metastasization of C57BL/6 mice carrying B16-F10 melanoma through downregulation of tumor promoting factors such as MMP-2, MMP-9, VEGF, urokinase-type plasminogen activator (uPA) and uPA receptor." (PMID 32948083, 2020). "IHC staining showed decreased expression of EZH2, CCL5, and MMP2 in tumor tissues." (PMID 31855281, 2020). "However, down-regulating the expression of MMP2 can reduce tumor cell proliferation, clonal growth and metastasis, and promote tumor cell apoptosis." (PMID 33115469, 2020). "Furthermore, from the previous study, MMP-2 is not only a tumor marker in NPC, but also related to lymph node metastasis and poor survival outcome." (PMID 33096744, 2020). "Besides, tumor tissues of LINC00662 overexpression group had more positive expression of MMP-2 than vector group, whereas, tumor tissues of LINC00662 inhibition group had lower positive expression of MMP-2 than siNC group." (PMID 31900207, 2020). "But it also can stimulate tumor cells to produce MMPs, specifically MMP-2 and MMP-9." (PMID 33178600, 2020). "MMP-2, which is secreted by cancer cells and tumor stromal cells, is considered as a biomarker in many types and grade of cancers, and MMP-2 has been generally accepted as a target for active targeting for tumors." (PMID 33330618, 2020). "MMP-2 regulates cancer cell behaviors, including tumor growth and migration." (PMID 32430842, 2020). "Among all of the tumor samples, MMP-2 was expressed in 66% of them and TIMP-2 in 53%." (PMID 32751899, 2020). "E-cadherin and MMP-2 are key factors in tumor migration and invasion." (PMID 33330466, 2020). "We further found that Porf-2 can inactive Rac1 and decrease MMP-2/9 protein level in tumor cells." (PMID 32676454, 2020). "Moreover, tumour progression‐related proteins such as MMP‐2, MMP‐9, uPA, VEGF, Cyclin D1 and XIAP were all decreased by imipramine in U‐87 MG and GBM8401 cells." (PMID 32149465, 2020). "Decreased levels of miR-320a in CAF-derived exosomes promote cell proliferation, migration, and metastasis; loss of miR-320a leads to de-repression of its target PBX3, activating MAPK pathway and up-regulation of CDK2 and MMP2; in vivo, miR-320a overexpression suppresses tumor growth and metastasis." (PMID 32957712, 2020). "Therefore, the intratumor activity of MMP-2 that is involved in tumor progression and metastasis was assessed using gelatin zymography." (PMID 32340166, 2020). "MMP2 facilitated tumor growth, invasion, angiogenesis, and metastasis 60-63." (PMID 33052224, 2020). "Whether F. nucleatum directly up-regulates SULF1 and/or MMP2 through epigenetic mechanisms or ECM remodeling by gene degradation plays a role in initial HNSCC tumor growth remains an interesting question warranting further investigations." (PMID 33218162, 2020).